S100A4 (S100 calcium binding protein A4)
Diseases named in the same sentence as S100A4 in open-access papers (continued):
Sharing a sentence is not in itself a finding about the gene and the disease.
tumor (continued). "Our result might be explained by considering that tumour tissue analysis by MS allows the inclusion of both cancer and stromal S100A4-positive cells, which are known to cooperate to drive tumour progression and metastasis." (PMID 25880590, 2015). "In addition to the elucidation of the molecular mechanisms underlying the role of S100A4 in cancer, the S100A4 protein may have clinical utility as a prognostic, predictive or diagnostic tool and may provide a novel method for the prevention and treatment of tumor metastasis." (PMID 25339497, 2015). "S100A4 downregulation in tumor cells greatly impairs their ability to develop tumors in vivo." (PMID 25677816, 2015). "In light of our results, specific inhibition of S100A4 could be safely applied in complementing anti‐tumor vaccination." (PMID 26734465, 2015). "S100A4 is a marker of fibroblasts in tissues undergoing remodelling, for example in fibrosis in the renal interstitium, while FAP expression is associated with activated fibroblasts in tumour stroma and fibrotic disease." (PMID 25978616, 2015). "How S100A4 regulates VEGFA expression in tumor cells, and whether it is directly or indirectly regulated, are interesting questions that remain to be answered." (PMID 25677816, 2015). "Furthermore, recent studies on mice that lack the S100A4 gene, and on mice carrying tumor cells subjected to siRNA-mediated S100A4-downregulation, have shown suppression of tumor development and metastasis formation." (PMID 23929008, 2014). "As the generation of a new vascular supply is causally involved in the progression of the majority of solid tumors, siRNA-mediated inhibition of endothelial S100A4 could provide an effective anti-tumor RNAi medicine." (PMID 23929008, 2014). "Additionally, the occurrence of S100A4 in the tumor-stroma microenvironment aggravates metastasis formation, partially by remodeling the extracellular matrix or the recruitment of factors of the immune system." (PMID 24952599, 2014). "A fibroblast secreted protein-1 (FSP1), also called S100A4 and mts1, is secreted by both fibroblasts and cancer cells, and also possibly by macrophages, making the environment more favourable to tumor progression by regulating inflammation and angiogenesis and promoting metastasis." (PMID 24883045, 2014). "The results suggest that S100A4 in endothelial cells is involved in tube formation and thus siRNA-mediated inhibition of endothelial S100A4 could provide an effective anti-tumor RNAi medicine." (PMID 23929008, 2014). "Immunohistochemistry on sequential sections from the same tumor revealed that Ring1B expression is enhanced in those regions that displayed positive nuclear staining for S100A4, suggesting that Ring1B expression could be linked to a poor IDC prognosis." (PMID 24742605, 2014). "It suggests a possible role of S100A4 in regulating endothelial cell growth, which may, in part, account for a drastic inhibition of neoangiogenesis in mS100A4 siRNA-administered tumor." (PMID 23929008, 2014). "Furthermore, the effect of S100A4 knockdown on angiogenesis and tumor growth was examined in a xenograft cancer model." (PMID 23929008, 2014). "We previously reported that S100A4 is expressed in both tumor cells, and endothelial cells." (PMID 23929008, 2014). "One therapeutic aim is to target S100A4 gene expression within the tumor cells." (PMID 24952599, 2014). "If suppression occurs, it would suggest that inhibition of S100A4 could reduce tumor angiogenesis and by inference, tumor metastatic ability, which would have important implications for the development of cancer therapeutics." (PMID 23929008, 2014). "There are few data on the in vivo implication of extracellular S100A4 protein in tumor growth." (PMID 24023743, 2013). "Furthermore, we also observed a significant association between high S100A4 expression and several clinicopathological parameters (lymph node metastasis, nodal status, TNM stage, and tumour depth)." (PMID 24188373, 2013).
tumor (continued). "However, our results suggest that the combination of E-cadherin and S100A4 expression at the invasive margin of CRC is superior to tumor budding for predicting prognosis." (PMID 23783026, 2013). "Moreover, the depletion of S100A4 by shRNA, which knocks down intracellular and extracellular expression, demonstrates the prominent role of the tumor cell in the crosstalk between tumor and stromal cells." (PMID 24023743, 2013). "One candidate biomarker for the progression and prognosis of multiple malignant tumours is S100A4." (PMID 24188373, 2013). "There is a growing body of evidence that S100A4, like others members of the S100 family, may play an important role in tumor angiogenesis, tumor growth and cancer metastasis." (PMID 24023743, 2013). "Tumor angiogenesis analysis from these cells showed a dramatic increase in vascularization, phenomenon that could explain the role of secreted S100A4 by tumor cells, therefore increasing in part the measured tumor growth." (PMID 24023743, 2013). "Therefore, S100A4 becomes a promising target for therapeutic applications by blocking angiogenesis and tumor progression." (PMID 24023743, 2013). "Additionally, there were significant associations between S100A4 expression and several clinicopathological parameters (tumour location, lymph node metastasis, nodal status, TNM stage, and tumour depth)." (PMID 24188373, 2013). "This demonstrates on the one hand the important role of S100A4 on tumor development and on the other hand that silencing is more specific than overexpression for determining the role of a factor in cell biology because the problems associated with overexpression are avoided." (PMID 24023743, 2013). "Loss of E-cadherin was associated with cell grade, macroscopic type, perineural invasion, and tumor budding, β-catenin with microsatellite instability and tumor site, and S100A4 with growth type, macroscopic type, AJCC stage, lymphovascular invasion, and perineural invasion." (PMID 23783026, 2013). "Interestingly, while a slight down-regulation of S100A4 expression was observed in EL4 tumor-carrying animals, induction of EAE rather increased the S100A4 RNA expression in splenic Ly6C++ cells." (PMID 23667563, 2013). "S100A4 is a member of the Ca2+-binding protein S100 family, which has been widely found to be over-expressed in highly metastastic cancers and characterized as a marker of tumour progression." (PMID 23469180, 2013). "Immunohistochemical staining for S100A4, ephrin-A1 and osteopontin was performed on tissue microarrays containing primary tumor samples from a cohort of 217 prospectively recruited NSCLC patients, and associations with clinicopathological parameters were investigated." (PMID 22853000, 2012). "Subsequently, it binds to transcription factors and drives the uncontrolled expression of target genes implicated in cell proliferation, transformation, and tumor progression, such as Myc, matrix metalloproteinase 7, Axin-2, the cell adhesion molecule L1-CAM, the metastasis gene S100A4, and others." (PMID 22640921, 2012). "The role of S100A4 in tumor progression and metastasis is well documented." (PMID 22558457, 2012). "S100A4 plays an important role in tumor metastasis, due to its effects on tumor cell migration." (PMID 23166536, 2012). "We used metastasis-related gene mRNA microarrays to analyze the dynamic change of genes before and after S100A4 silencing, which may provide a helpful insight into the potential mechanism of tumor growth and metastasis inhibition due to S100A4 silencing." (PMID 22200787, 2012). "Based on the reported biological effects of ephrin-A1 and osteopontin, S100A4-induced expression of these molecules may be one of several mechanisms by which S100A4 promotes tumor progression." (PMID 22853000, 2012).
tumor (continued). "One might also speculate that S100A4 could inhibit tumor progression in the early stages of NSCLC development, while promoting metastasis at later disease stages, similar to the cytokine transforming growth factor β." (PMID 22853000, 2012). "S100A4 might be implicated in this process as well, since previously it has been shown that S100A4 could trigger MMP activation in tumor cells and synovial fibroblasts and in endotheial cells, [ and 41]." (PMID 20442771, 2010). "Furthermore, we showed that the S100A4/RANTES interplay significantly promotes metastatic features of tumor cells." (PMID 20442771, 2010). "S100A4, a small Ca2+-binding protein of the S100 family, is an essential pro-metastatic mediator in tumor and is categorized as a useful prognostic marker in numerous tumor types." (PMID 20442771, 2010). "Two of its members, S100A4 and A13, are thought to be pro-angiogenic in tumor development." (PMID 21139687, 2010). "Secretion of S100A4 by tumor cells has been previously demonstrated in vitro." (PMID 20515499, 2010). "S100A4-positive cells were increased in MCF7S1 + HMF3s tumours compared with MCF7S1 tumours." (PMID 20723242, 2010). "However, the events implicated in upstream and downstream pathways regulating the activity of the extracellular S100A4 protein in the tumor milieu remain unsolved." (PMID 20442771, 2010). "We assume, therefore, that stimulation of MCF7S1 cell growth triggered by human fibroblasts in an orthotopic mouse model is dependent on the pronounced development of host-derived stroma that supply tumour growth by the mouse-derived cytokines, S100A4 and MMPs." (PMID 20723242, 2010). "Stimulation of the invasive phenotype of tumour cells in 3D co-cultures with fibroblasts could be correlated with increased production of S100A4 and MMP-2." (PMID 20723242, 2010). "Thus RANTES-overexpressing cells raise significantly more (82-fold) metastases in lung compared with control tumor cells in S100A4+/+ mice, whereas this difference is notably lower (5.6-fold) in the S100A4 (−/−) mice." (PMID 20442771, 2010). "Furthermore, T-cells are attracted to the tumour milieu by S100A4 and thereby inducing an inflammatory response in the tumour microenvironment through elevation of T-cell specific cytokines." (PMID 20723242, 2010). "The markedly reduced tumour size in MDA/RLN2 xenografts may have been a result of the reduced S100A4 production within the tumour cells." (PMID 18718015, 2008). "Our results indicate that long-term exposure to relaxin confers growth inhibitory and anti-invasive properties in oestrogen-independent tumours in vivo, which may in part be mediated through a down-regulation of S100A4." (PMID 18718015, 2008). "Taken together, we may speculate that S100A4 is an active metastasis regulator that is secreted by tumour cells and tumour-activated stromal cells." (PMID 15900299, 2005). "Extracellular S100A4 targets tumour or endothelial cells by binding to an as yet unknown receptor and triggering a signal transduction cascade and/or perhaps by internalisation followed by interaction with the intracellular target proteins." (PMID 15900299, 2005). "Furthermore, VMR tumour cells release factor(s) that triggers a release of S100A4 from immortalised fibroblasts." (PMID 15900299, 2005). "Since S100A4 was intensely immunostained in metastatic tumours as compared to the primary tumours, we wondered whether its mRNA transcripts were also increased to the same degree as its protein expression." (PMID 16265347, 2005). "Expression of S100A4 protein in different types of tumours may suggest the ability of this protein to promote invasiveness and metastasis of various human neoplasms." (PMID 15900299, 2005).
tumor (continued). "S100A4 appeared to be associated with T lymphocytes (not shown), but the close association of T and B lymphocytes in the tumours prevented a firm conclusion to be drawn." (PMID 11875708, 2002). "S100A4 belongs to the S100 subfamily of calcium-binding proteins and has been suggested to be directly involved in invasion and metastasis of rodent and human tumour cells." (PMID 10389988, 1999). "Across cancers, S100A4 expression is associated with poor survival and has a negative impact on the anti-tumor immune response, but the mechanism by which S100A4 modulates this response may vary in different cancers." (PMID 40078995, 2025). "Therefore, blocking S100A4 stimulation of tumor cells may be a potential strategy to address the poor efficacy of neoadjuvant therapy." (PMID 40772225, 2025). "Individual macrophage subsets possess distinct metabolic profiles; our analysis highlighted a specific cell subset, which persisted throughout lung carcinogenesis and was observably defined by the expression of S100a4 that had previously not been implicated in tumor-associated alveolar macrophages." (PMID 40658605, 2025). "So, S100A4 may also mediate the regulatory function of STC1 on the tumor microenvironment." (PMID 37400459, 2023). "In summary, we showed for the first time in a Caucasian AGE/S population that S100A4 expression is a negative prognostic marker in these tumor entities that predicts, especially in low-risk staged tumors, the development of metachronous metastases and poor prognosis." (PMID 35326507, 2022). "Importantly, S100A4(+)/HIF-1α(−) tumor cells were recruited along the surface of host preexisting vessels in vascular-rich areas of non-Ps perinecrotic lesions, whereas high VEGFA mRNA expression was found in S100A4(+)/HIF-1α(+) GBM cells in the adjacent areas." (PMID 35392912, 2022). "By inducing EMT, the deregulated miR-296/S100A4 axis could promote tumor invasion in human OC." (PMID 35317077, 2022). "However, although a sensitivity of 97.47% in PCA3 and a specificity of 90.32% in S100A4 was reached, the detection signal level could be variable in some analyses owing to tumor heterogeneity." (PMID 36613987, 2022). "Due to the requirement of PPAR-γ induction in this process, this study thus suggests that blocking macrophagic S100A4 may reverse this alternative polarization toward a protumor phenotype and thereby reduce the effects of TAMs on tumor initiation, malignancy and cancer treatment resistance." (PMID 34145030, 2021). "Therefore, the expression of S100A4 may predict the response of metastatic tumor cells to irradiation and treatment with a Chk1 inhibitor." (PMID 34124754, 2021). "Since S100A4 protein could maintain cell stemness, which is important in promoting cancer metastasis, therefore, we performed in vitro sphere formation and in vivo tumor initiation assays." (PMID 34035222, 2021). "Furthermore, it has been demonstrated that S100A4 secreted by either tumor and/or stromal cells may lead to pro-metastatic events such as cell motility, invasion, and angiogenesis." (PMID 33946884, 2021). "Genes upregulated in both tumor and TAS of BA PCa patients as compared to WA included cell cycle markers CD19, CD2, CD53 and CD80, interferon response factor 8 (IRF8), phosphoinositide 3-kinase (PIK3CA), mechanistic target of rapamycin (mTOR), and metastasis-associated protein S100A4." (PMID 34316327, 2021).
tumor (continued). "Extracellular S100A4 in the TME induces the release of pro-inflammatory factors (e.g., interleukin 6 (IL-6), interleukin 8 (IL-8), and C-X-C motif chemokine 10 (CXCL10)), which then converts monocytes into tumour-associated macrophages (TAMs), resulting in metastasis and drug resistance." (PMID 32722137, 2020). "Whether S100A4 can influence tumor development by regulating autophagy is largely unknown." (PMID 29449540, 2018). "Furthermore, PD407824 reduced the mRNA and protein level of S100A4 protein in 4T1.2 tumor cells." (PMID 29507695, 2018). "The use of a TLR4-deficient mouse tumor model, as well as in vitro experiments in which the S100A4 receptor was blocked in MDSCs, finally established that the activation of TLR4–ERK signaling by extracellular S100A4 is responsible for the resistance of MDSCs to intrinsic apoptosis induction." (PMID 29556233, 2018). "Furthermore, autophagy markers were detected in tumor tissue sections from S100A4−/− and WT mice." (PMID 29449540, 2018). "Parallel to the previous studies, our study did not demonstrate a significant association of the S100A4 expression with the age, gender, tumoral differentiation, the size of the tumor, the presence of vascular invasion, distant metastases, and presence of recurrences in CRC." (PMID 30111999, 2018). "Therefore, we did not attribute the reduced tumor growth in S100A4-deficient mice to impaired immunosuppressive capacity of the S100A4−/− MDSCs but to impaired MDSC accumulation." (PMID 29556233, 2018). "Thus, application of RNAi-based therapeutics for the knockdown of S100A4 expression in tumor cells might be a practical approach to effectively and efficiently suppress cancer metastasis and prolong the disease-free survival of cancer patients." (PMID 29069865, 2017). "Similarly, other small molecule peptide-drug conjugates having high affinity to S100A4 could be also developed to control tumor metastasis." (PMID 29069865, 2017). "As a biomarker, the detection of S100A4 level in tumor tissues or non-invasively in body liquid specimens could predict prognosis and metastasis of cancer patients in early stages and the inhibition of S100A4 expression also restricted the metastasis potential in vivo." (PMID 29069865, 2017). "In addition, S100A4-defiecient mice displayed less tumor formation and metastasis." (PMID 27793047, 2016). "In addition, S100A4 attracted T-cells to the primary tumor and pre-metastatic lungs, suggesting that it could affect the homing of T-cells." (PMID 25884510, 2015). "Therefore, therapeutic approaches targeting RAGE or intervening in RAGE-dependent signaling early in tumor progression might represent alternative strategies restricting the S100A4-induced metastasis in CRC." (PMID 24952599, 2014). "Although endothelial cells have not been shown to secrete S100A4, and its biological function in these cells is unknown, the endothelial S100A4 may be pertinent for the regulation of tumor angiogenesis and metastasis, and thus an attractive target for cancer therapy." (PMID 23929008, 2014). "We first examined whether endothelial cells of tumor microvessels express S100A4." (PMID 23929008, 2014). "Therefore, it would be interesting to investigate whether administration of an agent that inhibits both mouse and human S100A4 could suppress the metastasis of xenografted human tumor cells in immuno-compromised mice." (PMID 23929008, 2014). "However, S100A4 in tumor cells is also involved in invasion and metastasis." (PMID 23929008, 2014). "Based on our findings on the importance of the S100A4-RAGE interaction, therapeutic approaches targeting RAGE or intervening in RAGE dependent signaling early in tumor progression might represent alternative strategies restricting the S100A4-induced metastasis in CRC." (PMID 24952599, 2014).